VWF (von Willebrand factor)
Diseases named in the same sentence as VWF in open-access papers (continued):
Sharing a sentence is not in itself a finding about the gene and the disease.
ischemic stroke (75 papers, 2011 to 2025). A stroke disorder caused by obstruction of blood flow to the brain, due to thrombotic (local blood clot formation) or embolic (due to a blood clot or other material traveling from another site) event. "After adjusting these potential biomarkers for clinical risk factors, lower vWF (OR = 0.197, p = 0.006) remained an independent risk factor for s‐HT in ischemic stroke patients." (PMID 40135640, 2025). "The elevated vWF serum levels have been reported as a predictor of an increased risk of the first ischemic stroke." (PMID 31701356, 2020). "Reassuming, a coincidence between increased level of vWF and different types of ischemic stroke has been confirmed, making this factor a potential risk indicator of cerebrovascular diseases." (PMID 31701356, 2020). "In recent years, von Willebrand factor (vWF) has been consistently implicated in the epidemiologic literature as a risk factor for ischaemic stroke." (PMID 29847840, 2018). "In conclusion, our results show the importance of ADAMTS13 in cerebrovascular disease and put forward the VWF/ADAMTS13 axis as a potential biomarker for ischemic stroke risk and severity." (PMID 28591212, 2017). "Obesity is a well-recognized risk factor for thrombotic cardiovascular complications including ischemic stroke, and it has been linked with increased plasma vWF." (PMID 28570705, 2017). "In the Rotterdam study, elevated VWF levels predict the highest risk of ischemic stroke in general population." (PMID 28634421, 2017). "Several studies have linked chronically increased plasma concentrations of vWF to an increased risk for thrombotic complications, including acute coronary syndrome and ischemic stroke." (PMID 28570705, 2017). "In univariate analysis, ADAMTS13 activity during admission was associated with platelet values at the same time point (r = 0.12, p = 0.01) and VWF: Ag levels were associated with age (r = 0.439, p = 0.04), previous ischemic stroke (r = 0.9176, p = 0.031), and glucose levels (r = 0.64, p = 0.049)." (PMID 40217918, 2025). "Moreover, VWF is considered an effective biomarker for predicting the risk of death in ischemic stroke patients." (PMID 40066310, 2025). "The observed discrepancy of vWF levels between bad outcomes and s‐HT after ischemic stroke may relate to differing underlying mechanisms contributing to poor outcomes and BBB damage." (PMID 40135640, 2025). "However, multivariable MR analyses adjusting for genetic associations with VWF eliminated the apparent link between factor VIII and ischemic stroke, suggesting VWF as the primary driver of this association." (PMID 39628323, 2024). "Migraine also has been associated with increased prevalence of patent foramen ovale and increased levels of von Willebrand factor, which might contribute to increased risk of ischemic stroke." (PMID 37310926, 2023). "Moreover, single-nucleotide variations in VWF gene increase the risk of ischemic stroke and cardiovascular disease." (PMID 37240845, 2023). "Interestingly, high VWF antigen levels are associated with aortic arch and carotid artery calcification in ischemic stroke patients." (PMID 33618719, 2021). "Additionally, it appeared that serum Mg level was inversely correlated with von Willebrand factor status, which in turn was positively associated with the incidence of ischemic stroke." (PMID 32042391, 2020). "Indeed, in mouse models of ischemic stroke, VWF deficiency is associated with reduced neutrophil infiltration in the ischemic hemisphere." (PMID 31921147, 2019). "Furthermore, polymorphisms in the GPIBA gene that lead to enhanced VWF-GPIbα interactions are associated with an increased risk of ischemic stroke in humans." (PMID 31921147, 2019). "Moreover, several conditions, including the GPIbα Kozak polymorphism, GPIbα variants with increased binding to VWF and high VWF levels, have all been reported to be associated with an increased risk of ischemic stroke in humans." (PMID 21914206, 2011).
ischemic stroke (continued). "We recently demonstrated that VWF deficient mice were protected from ischemic stroke." (PMID 21914206, 2011). "In patients with VWF:Act/Ag ratio ≤0.7 less ischemic stroke events were observed (HR: 0.11; 95% CI = 0.01–0.85)." (PMID 38896804, 2025). "We found elevated VWF:Ag levels in the ischemic stroke with migraine group, suggesting a possible supra‐additive effect." (PMID 40022462, 2025). "In patients with VWF:Act/Ag ratios ≤0.7 observed in the early postoperative phase significantly less ischemic stroke events (HR: 0.11; 95% CI = 0.01–0.9, p = 0.02) were observed." (PMID 38896804, 2025). "VWF:Ag levels were higher in the ischemic stroke with migraine group (170 %; adjusted β = 31%; 95% CI = 6%–56%) compared with group 4, but not in the other groups." (PMID 40022462, 2025). "Unlike other studies, we used ELISA to test the levels of vWF in newly recruited ischemic stroke patients to assess the clinical transformation ability of vWF using Olink proteomics." (PMID 40135640, 2025). "These analyses initially showed an association of both genetically proxied VWF and factor VIII with ischemic stroke." (PMID 39628323, 2024). "In the context of an experimental mouse model investigating cerebral I/R injury in ischaemic stroke, a notable decrease in NET formation following ischaemia was detected in VWF-deficient mice compared to their wild-type counterparts." (PMID 38654328, 2024). "In this study, we evaluated the association of the VWF rs61748511 T > C, TNF-alpha rs1800629 G > A and GST rs4025935, rs71748309 gene variants with risk of ischemic stroke in the Saudi population." (PMID 37240845, 2023). "Other investigators have noted PAI-1 as well as vWF decorating NETs in the setting of ischemic stroke, and NETs have a well know role in thrombus formation." (PMID 36999030, 2023). "It has been reported that the VWF has a role in ischemic stroke, and that it can be a target for stroke treatment." (PMID 37240845, 2023). "Disruption of this interaction, either with anti-vimentin antibodies or with a von Willebrand Factor fragment, positively affected experimental models of ischemic stroke." (PMID 37356720, 2023). "Previous studies have demonstrated that targeted inhibition of VWF induces thrombolysis when administered in vivo in animal models of ischemic stroke." (PMID 36558901, 2022). "Pharmacologically targeting the vimentin/VWF von Willebrand Factor interaction through the A2 domain can promote improved reperfusion after ischemic stroke." (PMID 35453578, 2022). "It is responsible for the removal of von Willebrand factor (vWF)-platelet strings from activated endothelial cells; the relationship of vWF/ADAMTS13 is associated with an increased risk of ischemic stroke." (PMID 35741047, 2022). "vWF level measurements were performed at the following intervals: ≤4 weeks of TIA or ischemic stroke (baseline), ≥14 days, and then ≥90 days." (PMID 35207321, 2022). "The genetic locus located within the ABO gene plays a role in hemoglobin concentration, hematocrit, von Willebrand factor, myocardial infection, coronary artery disease, ischemic stroke, type 2 diabetes, and venous thromboembolism." (PMID 35096865, 2021). "What seems practically important is that the vWF levels differ among various clinical and etiological subtypes of ischemic stroke, which must be taken into account when conducting laboratory and clinical studies on this promising biomarker." (PMID 31701356, 2020). "Thrombi from ischemic stroke patients contain on average 20.3 ± 10.1% of VWF, and VWF (especially endothelial cell-derived VWF) is proved to mediate ischemic stroke by promoting postischemic thrombo-inflammation in a brain ischemic/reperfusion injury model." (PMID 33343584, 2020). "The VWF-ADAMTS13 axis has been proven to play a significant role in the pathophysiological microcirculatory disturbance of ischemic stroke." (PMID 32849241, 2020).
ischemic stroke (continued). "Recent case-control studies also demonstrated that the higher plasma vWF or lower ADAMTS13 levels were closely associated with the risk of MI, ischaemic stroke." (PMID 32039706, 2020). "So far, numerous studies have investigated the histopathological composition of ischemic stroke thrombemboli and identified red blood cells (RBCs), fibrin, platelets, von Willebrand Factor (vWF) and white blood cells as main components." (PMID 33036337, 2020). "In this review, we discuss the current evidence for the thrombo-inflammatory activity of VWF with a focus on the VWF-GPIbα axis and discuss its implications in the setting of ischemic stroke." (PMID 31921147, 2019). "Given the dual role of VWF and GPIbα in both thrombosis and inflammation, the VWF-GPIbα axis has received quite some attention in the setting of ischemic stroke." (PMID 31921147, 2019). "Due to the close relationship between VWF and platelet aggregation as well as thrombus formation, research has focused on the correlation between high levels of VWF and cardiovascular/cerebrovascular diseases including ischemic stroke." (PMID 31379722, 2019). "It was reported that the volume of the cerebral infarct was significantly reduced with decreased VWF levels after ischemic stroke, whereas the volume of the cerebral infarct was increased with decreased ADAMTS13 levels." (PMID 31379722, 2019). "In summary, current evidence shows the involvement of the VWF-GPIbα interaction in a vicious circle of thrombotic and inflammatory responses in the ischemic stroke brain." (PMID 31921147, 2019). "Nonetheless, more clinical studies are needed to specifically address the contribution of VWF-mediated thromboinflammatory brain damage during ischemia and reperfusion in ischemic stroke patients." (PMID 31921147, 2019). "Our study reveals that chronic phase vWF-ag levels correlate with the amounts of visceral and pericardial type adipose tissue in patients with recent ischemic stroke of suspected cardiogenic origin." (PMID 28570705, 2017). "In mouse models of ischemic stroke, VWF activates thromboinflammatory pathways involved in postischemic inflammatory response and ischemia/reperfusion (I/R) injury, and complete deficiency of VWF is protective for cerebral infarction." (PMID 28634421, 2017). "While the association between VWF levels and thrombolysis outcome following AMI has been studied before, surprisingly, similar data regarding ischemic stroke are much more limited." (PMID 29410644, 2017). "In the past decades, inhibition of the action of VWF has become an attractive new antithrombotic strategy in ischemic stroke management." (PMID 29410644, 2017). "Hence ADAMTS13 and VWF could be independent risk factors for ischemic stroke." (PMID 28591212, 2017). "We studied the plasma levels of vWF antigen and their correlation with the amount of adipose tissue in different locations in patients with ischemic stroke of suspected cardiogenic origin or ESUS." (PMID 28570705, 2017). "For instance, the processes involved in the regulation of VWF expression during ischemic stroke and the specific contribution of VWF to the preceding pathophysiologic events await clarification." (PMID 24937073, 2014). "It is interesting to find that s‐HT patients in the retrospective study cohort had lower levels of serum vWF, which could efficiently distinguish s‐HT cases from ischemic stroke patients." (PMID 40135640, 2025). "In patients with VWF:Act/Ag ratio ≤0.7 less ischemic strokes were observed." (PMID 38896804, 2025). "Further studies are warranted to investigate the vWF dynamics after ischemic stroke." (PMID 40135640, 2025). "Our findings suggest that endothelial activation, indicated by increased VWF:Ag levels, may be more relevant than a procoagulant state alone in the pathophysiology of ischemic stroke in patients with a history of migraine." (PMID 40022462, 2025). "The crucial role of ADAMTS13 and VWF has been identified in the ischemic stroke development." (PMID 40217918, 2025).
ischemic stroke (continued). "Thus, the aim of this study is to investigate the correlation between ADAMTS13 activity and VWF antigen (VWF: Ag) levels in the outcomes, severity, and disability degree in patients with ischemic stroke." (PMID 40217918, 2025). "In contrast, in patients with VWF:Act/Ag ratio≤0.7 less ischemic strokes were observed." (PMID 38896804, 2025). "Future prospective trials should explore whether postoperative VWF profile measurements could guide antithrombotic adjustments to reduce the risk of GIB and hemorrhagic and ischemic stroke." (PMID 38896804, 2025). "Through the use of a combined retrospective and prospective study, vWF might be a novel blood biomarker for predicting s‐HT occurrence in ischemic stroke patients." (PMID 40135640, 2025). "Compared with non‐s‐HT patients, those with s‐HT had lower levels of vWF (26.57 [13.64–37.18] vs. 42.00 [26.02–55.52] ng/mL, p < 0.001) and could be efficiently distinguished from ischemic stroke patients (AUC = 0.735, p < 0.001)." (PMID 40135640, 2025). "Consequently, targeting VWF is promising as a compelling avenue for the advancement of novel therapeutic approaches for the management of ischaemic stroke." (PMID 38654328, 2024). "Elevated VWF levels immediately after lysis and at 24 h post-therapy have been shown to be an independent prognostic predictor for poor functional outcomes at 90 days for patients with ischemic stroke." (PMID 37342100, 2023). "The authors of the EuroCLOT study found that the genes of the ABO system are associated with the Von Willebrand factor and factor VIII levels, and therefore, if present in a polymorphic form, they are related, with a higher prevalence, to microlacunar ischemic strokes." (PMID 35741740, 2022). "Through the construction of a targeted Nb, the specific role of von Willebrand factor in ischemic stroke could be studied and the mechanism of VWF mediated by its A1 domain could be determined." (PMID 36426363, 2022). "For example, von Willebrand factor (VWF) is an important factor affecting ischemic stroke." (PMID 36426363, 2022). "VWF promotes shear stress-regulated platelet aggregation and platelet clearance and has been recently described to play a role as mediator of thrombo-inflammation in a mouse model of ischemic stroke." (PMID 34685717, 2021). "C1QA, FGG, FN1, and VWF could therefore be involved in atherogenesis progression in patients with CSC ischaemic stroke." (PMID 34356850, 2021). "had discussed that VWF-GPIbα is a thrombo-inflammatory axis in ischemic stroke." (PMID 33343584, 2020). "The results of marker discovery studies on plasma of ischemic patients presented markers, such as BNP, von Willebrand factor, ICAM-1, CRP, and interleukin-6, through biomarker research progress associated with causes of ischemic stroke, which differed from the biomarkers identified in our study." (PMID 32466277, 2020). "The dysregulated VWF-ADAMTS13 axis has great effects on ischemic stroke." (PMID 32849241, 2020). "Evidence for the involvement of VWF in ischemic brain injury comes from mouse studies showing that absence of VWF is associated with a significant reduction in ischemic stroke brain injury and improved functional outcome." (PMID 31921147, 2019). "Furthermore, anfibatide, a snake venom-derived GPIbα antagonist that specifically blocks platelet GPIbα binding to VWF had a potent protective effect in mouse models of ischemic stroke." (PMID 31921147, 2019). "Hence, further studies are needed to generate a more complete picture of the involvement of GPIbα in ischemic stroke, besides binding to VWF." (PMID 31921147, 2019). "However, randomized clinical trials with vWF inhibitors are needed to ultimately demonstrate the relevance of blocking vWF for the prevention or treatment of ischaemic stroke in this patient population." (PMID 29847840, 2018). "In particular, the combination of high amounts of VWF with low levels of ADAMTS13 could form a harmful imbalance for the development of ischemic stroke." (PMID 28591212, 2017).
ischemic stroke (continued). "Anfibatide has also been shown as a candidate to treat ischemic stroke in experimental models (the same may hold true for anti-VWF therapy) and deserves further investigation." (PMID 27766055, 2016). "As inhibition of GPVI-collagen and GPIb-vWF interactions is known to reduce pathological thrombosis with minimal effect on the physiological response to injury, especially with regards to ischemic stroke, there is considerable interest in exploiting these interactions for drug development." (PMID 27716777, 2016). "A number of studies have shown a link between vWF and ischemic stroke, and it has been presumed that excess vWF may increase thrombosis via a luminal mechanism." (PMID 24086636, 2013). "Furthermore, VWF: Ag levels were correlated with age (r = 0.439, 95% CI: 0.22, 8.57, p = 0.04), previous ischemic stroke (r = 0.9176, 95% CI: 9.19, 174.33, p = 0.031), and glucose laboratory values at the same time point (r = 0.64, 95% CI: 0.01, 1.29, p = 0.049)." (PMID 40217918, 2025). "Previous studies have shown that ADAMTS13 may become a promising pharmacological agent for ischemic stroke treatment through regulating VWF-mediated inflammation and thrombus formation in addition to its role in angiogenesis, the latter being especially important for ischemic stroke recovery." (PMID 31379722, 2019). "Notably, we and others have demonstrated that targeting VWF can also promote blood clot dissolution in the setting of ischemic stroke, which could be of particular relevance to overcome thrombolysis resistance of platelet-rich blood clots in patients." (PMID 31921147, 2019). "In our real-world prospective study, ADAMTS13 activity, VWF: Ag, VWF: Ag/ADAMTS13 Ratio, and their correlations with ischemic stroke severity indices were examined." (PMID 40217918, 2025). "Considering the protective effect of reduced VWF activity ratios against ischemic stroke and acknowledging the heightened risk of hemorrhagic and GIB in patients with low ratios, it may be prudent to reduce the intensity of antithrombotic regimens for people with low VWF activity ratios." (PMID 38896804, 2025). "The von Willebrand factor/ADAMTS13 axis has been shown to play a critical role in thrombotic disorders and in the prognosis of ischemic stroke outcomes." (PMID 40944050, 2025). "Another panel of 5 markers, consisting of S100B, vWF, MMP9, B-type neurotrophic growth factor (BNGF), and monocyte chemoattractant protein 1 (MCP1), can distinguish patients with ischemic stroke from healthy controls with 92% sensitivity and 93% specificity." (PMID 36313479, 2022). "This imbalanced vWF/ADAMTS-13 ratio is often observed in conditions like arterial thrombosis, ischemic stroke, pediatric stroke and even myocardial infraction in young women." (PMID 36295093, 2022). "Published studies have paid little attention to the correlations between Lp-PLA2 activity (or mass) and other ischemic stroke biomarkers, including CRP, MMPs, IL-6, TNF-α, VCAM1, ICAM1, S100B, vWF, BNGF, and MCP1." (PMID 36313479, 2022). "In animal models, von Willebrand factor (VWF) is involved in thrombus formation and propagation of ischemic stroke." (PMID 24937073, 2014). "Ischemic stroke differed significantly between both VWF:Act/Ag strata but not for the VWF:CB/Ag ratio strata." (PMID 38896804, 2025). "Interestingly, platelet-derived VWF was recently shown not essential for hemostasis and thrombosis, but instead fosters thrombo-inflammatory diseases such as ischemic stroke in mice via a GPIb-dependent mechanism." (PMID 27766055, 2016). "Only few papers are found in the literature studying the changes of certain hemostasis factors during the course of thrombolysis following ischemic stroke and up to our knowledge, none of them studied the levels of FVIII and VWF comprehensively in this respect." (PMID 29410644, 2017).